WDR97 (WD repeat domain 97)
Synonyms: KIAA1875
Tractability: No criterion of Open Targets' tractability assessment is met for any kind of drug.
Gene: Protein-coding gene on chromosome 8 (144,107,726 to 144,118,328, forward strand). Ensembl gene ENSG00000179698.
Homologues: Orthologues: dog WDR97 (62% identical).
Diseases named in the same sentence as WDR97 in open-access papers:
WDR97 is named in the same sentence as 1 disease in open-access papers, as found by Europe PMC text mining. Sharing a sentence is not in itself a finding about the gene and the disease.
WDR97 shares sentences with these, for which no sentence is quoted: tumor (1 paper).